FTO (FTO alpha-ketoglutarate dependent dioxygenase)
Diseases named in the same sentence as FTO in open-access papers (continued):
Sharing a sentence is not in itself a finding about the gene and the disease.
Obesity (continued). "This indicates that the association of the FTO rs9939609 A allele with the MetS was related in part to both the obesity component, but also the HDL component, suggesting that this genetic marker may have a broader relationship with individual components of this complex trait." (PMID 18339204, 2008). "For example, the susceptibility to obesity and T2DM is higher among people carrying genetic mutations of genes such as FTO (fat mass and obesity‐associated gene) or TCF7L2 (transcription factor 7‐like 2) if exposed to a high‐carbohydrate or high‐fat diet." (PMID 41567168, 2026). "The association between variants of the FTO and LEPR genes has been explored as contributing factors to obesity in various age groups; however, their role in GWG and BW in adolescent mothers and their offspring is uncertain." (PMID 42074056, 2026). "Fourth, specific loci, such as FTO and MC4R, contain distinct alleles associated with severe obesity or thinness." (PMID 38849463, 2025). "For example, polymorphisms in the FTO, MC4R, LEP, and LEPR genes have been significantly associated with obesity and hypertriglyceridemia in Mexican children aged 4–13 years (n = 718)." (PMID 40647298, 2025). "These elevated levels of FTO are also positively correlated with obesity, insulin resistance, and blood glucose indices, indicating a strong link between FTO and the pathogenesis of T2D." (PMID 41277875, 2025). "Because of its role in post-transcriptional regulation and adipogenesis, FTO has become one of the most frequently studied targets in genetic manipulation models of obesity." (PMID 41303351, 2025). "Specifically, it is confirmed that HDACi specifically targets HDAC1 and promotes the H3K27ac modification of fat mass‐ and obesity‐associated gene (FTO) and AlkB Homolog 5, RNA Demethylase (ALKBH5), which results in significant activation of FTO and ALKBH5." (PMID 39888307, 2025). "While FTO is widely recognized for its role in obesity and energy metabolism, these findings highlight its independent association with a lower skeletal muscle mass and sarcopenia." (PMID 40428823, 2025). "The FTO protein plays a role in the development of obesity by influencing the N6-methyladenosine (m6A) level in hormones involved in eating or adipogenesis." (PMID 40486662, 2025). "The m6A demethylase FTO, as an important gene related to regulating obesity, plays an important role in regulating animal fat metabolism." (PMID 39858193, 2025). "The situation is more complex for polygenic obesity, where only a few GWAS loci (e.g., FTO, TMEM18, CADM1/CADM2, NEGR1) have been functionally followed up thus far." (PMID 38849463, 2025). "Recent studies have highlighted that polymorphisms in genes such as FTO and the Melanocortin-4 Receptor gene (MC4R) influence susceptibility to post-treatment obesity, enabling risk stratification and personalized intervention planning." (PMID 41228239, 2025). "Previous research has shown that inhibition of FTO can prevent obesity and lead to growth retardation, underscoring its importance in metabolic regulation." (PMID 40356725, 2025). "In conclusion, we show that quercetin‐driven A. muciniphila modulates host BA metabolism in ILA/FTO/m6A/CYP8B1/CA coordinated manner to ameliorate diet‐induced obesity." (PMID 39888270, 2025). "First discovered in Europeans, single-nucleotide polymorphisms (SNPs) in FTO and close to MC4R are obesity-susceptibility loci that extensively replicate across various ancestries." (PMID 41302083, 2025). "Among these, the fat mass obesity gene (FTO), which affects adiposity and the development of T2D, has emerged as a predisposing factor." (PMID 40486662, 2025). "In the context of early severe obesity research, FTO (alpha-ketoglutarate-dependent dioxygenase FTO) has attracted significant attention from the scientific community." (PMID 40869388, 2025).
Obesity (continued). "Given the critical role of FTO in regulating metabolism, it is an attractive target for therapeutic intervention to combat obesity and related diseases." (PMID 39984825, 2025). "FTO expression was significantly upregulated in the obesity group (fold-change: 5.8 vs. 1.0; p < 0.001), while MC4R expression was markedly downregulated (fold-change: 0.1 vs. 1.0; p < 0.001)." (PMID 41423640, 2025). "The first enzyme that was reported to demethylate m6A modifications on mRNA was characterized as the fat mass and obesity-associated protein (FTO), also known as alpha-ketoglutarate-dependent dioxygenase." (PMID 39791911, 2025). "Most studies focus on the relationship between the FTO gene variation and obesity, body mass index, metabolic disease and tumor in different regions and ethnic groups." (PMID 41007963, 2025). "Genetic variations in FTO, BDNF, and MC4R genes, related to increased risk of weight gain, have been reported to be linked to elevated BMI and obesity risk in large-scale genome-wide association studies." (PMID 40423790, 2025). "Inhibiting FTO has shown promise in reducing obesity and combating cancer by modulating the FTO-m6A-YTHDF2 axis." (PMID 40040878, 2025). "The detected interactions between low PA and the FTO rs1421085 or the TMEM18 rs7561317 increased all obesity-related outcomes." (PMID 39283705, 2025). "FTO SNP rs9939609 has been proven within different populations, including the South-Asian ethnicity, to be strongly related to various indices of obesity." (PMID 41190148, 2025). "While numerous studies have demonstrated that FTO can promote the progression of obesity and diabetes." (PMID 40356725, 2025). "Regarding FTO and obesity, results from this study are inconsistent with the latest published literature." (PMID 39925495, 2025). "Further research on larger cohorts is necessary to validate these preliminary findings and to elucidate the mechanisms of epigenetic regulation of FTO in the context of early obesity." (PMID 40869388, 2025). "Fat volume and obesity-related genes (e.g., the FTO gene) are important candidate genes affecting energy metabolism." (PMID 41007963, 2025). "FTO expression was significantly upregulated in patients with obesity (fold-change: 5.8 vs. 1.0, p < 0.001), showing a parallel elevation with adiponectin and BMI at the group level." (PMID 41423640, 2025). "The results demonstrated increased methylation levels in a portion of the FTO promoter region in individuals with obesity compared to the control group." (PMID 40869388, 2025). "This aligns with findings that FTO gene variations influence energy regulation, appetite, and metabolism, underscoring their impact on obesity across different ethnic and demographic groups." (PMID 40630163, 2025). "There is growing evidence that dietary and lifestyle modifications can significantly influence the expression of genes, including the FTO gene, which plays a critical role in energy homeostasis and obesity." (PMID 40630163, 2025). "Accordingly, the present study aimed to evaluate the expression of MEG3, FTO, and ATF4 in PBMCs from children with obesity and to assess their associations with added sugar intake and the expression of lipogenesis-related genes." (PMID 40806129, 2025). "While FTO is exclusively polygenic, MC4R represents a unique case: rare mutations cause monogenic obesity, whereas common polymorphisms act as major polygenic risk factors." (PMID 41302083, 2025). "Our analysis showed significant negative correlations between added sugar intake and the expression of SREBP1, ACACA, and FTO in PBMCs from children with obesity." (PMID 40806129, 2025). "Dysregulation of m6A is implicated in several diseases: METTL3 overexpression in glioblastoma promotes tumorigenicity by stabilizing oncogenic transcripts, while FTO upregulation contributes to obesity and chemoresistance in leukemia." (PMID 40870000, 2025).
Obesity (continued). "In studies conducted in adults, SNPs in the genes FTO, MC4R, TMEM18, TNNI3K, SEC16B, GNPDA2, and POMC are strongly associated with obesity risk." (PMID 40722558, 2025). "Several studies suggested that the FTO and TCF7L2 variants were the most robust genetic predictors for obesity and T2D in SA, respectively which is similar to the findings in European research." (PMID 39283705, 2025). "FTO removes methyl groups from RNA m6A marks, directly promoting obesity through m6A RNA modifications." (PMID 40429638, 2025). "The knowledge about the participation of genes like Fat mass and obesity-associated (FTO) and Transmembrane protein (TMEM) 18 and adipokines like leptin and adiponectin, in asthma, under the influence of obesity, is still scarce." (PMID 39159917, 2025). "This study evaluated MEG3, FTO, and ATF4 expression in PBMCs from children with obesity and their associations with added sugar intake and lipid metabolism genes." (PMID 40806129, 2025). "HBM has been reported to alter the DNA methylation of the FTO gene, well known for its variance among individuals and its strong correlation with obesity." (PMID 40004988, 2025). "This shift in fat cell phenotype supports energy conservation and increases fat storage, providing a possible mechanism by which FTO variations contribute to obesity-related traits." (PMID 40055285, 2025). "Clinical studies indicate that insulin sensitivity and engagement in physical activity have been observed to lessen the impact of the FTO genotype on obesity‐related characteristics." (PMID 40066229, 2025). "Genes implicated in monogenic obesity include POMC, LEP, LEPR, MC3R, and MC4R, while polygenic obesity involves variants in genes such as FTO, UCP1-3, MC4R, ADRB1-3, and SLC6A14." (PMID 41302083, 2025). "The combined effects of common variants or epistasis in FTO and MC4R have been investigated, showing significant effects on obesity and related traits in children and adolescents." (PMID 41082226, 2025). "metformin (Glucophage), adiponectin, FTO inhibitors, and anti-inflammatory interventions represent promising approaches to disrupt the biochemical pathways that link obesity and cancer." (PMID 40040878, 2025). "Other NPY2R variants, such as rs12649641, rs2342676, and rs6857530, have additive effects with other significant obesity–depression genes (e.g., FTO and MC4R)." (PMID 41375608, 2025). "Neuronal m6A demethylase FTO promotes obesity via enhancing KIF1A-dependent release of appetite-stimulating neuropeptides." (PMID 40634669, 2025). "The established obesity gene FTO is mainly found in animals and serves as an RNA demethylase, regulating growth and development." (PMID 40282280, 2025). "For example, catechin EGCG, an anti-obesity compound found in green tea, has been identified as an FTO inhibitor that can reduce fat mass and improve glucose metabolism, while also exerting anti-cancer effects." (PMID 40040878, 2025). "A 2021 study conducted on peripheral blood mononuclear cells from 16 patients with early-onset obesity provided new insights into the role of FTO in regulating metabolic processes." (PMID 40869388, 2025). "In another example, the detection of the interaction of FTO with physical activity for obesity was highly dependent on the amount of physical activity." (PMID 39315585, 2025). "Rather than acting independently, environmental exposures, including diet quality, physical activity, socioeconomic conditions, and psychosocial stress, interact with genetic predispositions (e.g., FTO, MC4R, LEP) to modulate obesity risk." (PMID 41302083, 2025). "Among multiple reports, both FTO and ALKBH5 are linked to cancer, FTO is linked to obesity, and ALKBH5 is linked to regulation of the hypoxic response and is a hypoxia-inducible factor target gene, i.e. is upregulated in hypoxia." (PMID 40874592, 2025).
Obesity (continued). "The regions showing association with obesity‐related phenotypes are located at 11q11 (OR4P4, OR4S2, OR4C6), 1p21.1 (AMΥ1), 10q11.22 (NPY4R), 10q26.3 (CYP2E1), 16q12.2 (FTO), 16p12.3 (GPRC5b), and 4q25 and have been associated with adult obesity as well." (PMID 41082226, 2025). "Increasing data indicates that SNPs and rare mutations in genes such as FTO, MC4R, LEPR, and POMC influence not only the risk of obesity but also significantly impact weight loss, WR, and metabolic outcomes following bariatric surgery." (PMID 41226372, 2025). "A recent GWAS with 700,000 participants identified 941 SNPs linked to BMI, with key genes like FTO and MC4R contributing to polygenic obesity." (PMID 40551726, 2025). "These variants mapped to well-established obesity-related genes and loci, such as POC5, MC4R, TMEM18, and the FTO locus." (PMID 38200577, 2024). "While much of the FTO research has concentrated on obesity, its potential involvement in neuropsychiatric disorders is gaining traction, supported by both preclinical and translational studies." (PMID 39080362, 2024). "Dysregulation in cellular programming can lead to an excess of adipocyte formation, contributing to obesity, such as leptin can regulate Plin5 M6A methylation by promoting FTO to affect the lipid metabolism and energy consumption." (PMID 39390356, 2024). "The FTO A variant increases the risk by 3.54 times and physical inactivity increases the risk by 6.37 times for class III obesity." (PMID 38610209, 2024). "For example, there is evidence for eQTLs (for IRX3 and FTO), chromatin looping, TF motifs, DNase I hotspots, and histone mark broadPeaks for rs1421085, a SNP previously identified for obesity." (PMID 38167104, 2024). "The data were confirmed by the UK Biobank, indicating the pleiotropic effect of FTO on both obesity and OP." (PMID 39336743, 2024). "Obesity-induced overexpression of FTO decreased the m6A modification of pri-miR-192, inhibiting the generation of miR-192." (PMID 38486141, 2024). "Although it was first found as an obesity-related gene, numerous subsequent studies led to a conclusion that FTO is a key player in m6A RNA methylation owing to its significance in regulating mRNA processing, maturation and translation." (PMID 38545555, 2024). "The FTO and MC4R gene are two of the verified obesity-related variants, but evidence from ethnic minorities in China is limited." (PMID 38279121, 2024). "Numerous SNPs of the FTO gene were investigated for their possible role in obesity; as rs178117449, rs9939609 rs3751812, rs1421085, rs9930506 (has the greatest effect on body weight and composition), and rs7202116." (PMID 39706986, 2024). "In addition to gender, it seems that an obesity-associated gene (FTO), the rs9939609 A-allele, is connected to obesity, increased caloric consumption, and higher concentrations of acyl-ghrelin (AG); nevertheless, the risk of obesity associated with this allele may be reduced by exercise." (PMID 39125635, 2024). "Given that FTO gene expression is the highest during the growth period and decreases with age, special attention should be paid to the interactions between obesity‐related genes and diet in children and adolescents." (PMID 38556726, 2024). "In this research a thorough examination was performed to elucidate the connection between various FTO gene SNPs and overweight or obesity in children and adolescents." (PMID 38973101, 2024). "Further studies in homogenous groups of patients with varying degrees of obesity would be necessary to understand the effect of FTO genetic variations on systemic insulin resistance and the specific effects on bone." (PMID 39336743, 2024). "Some previously published analyses of the Polish population show that the influence of SNPs in the first intron of the FTO gene on obesity is modulated by age and gender." (PMID 38892547, 2024).
Obesity (continued). "For example, Tan and Mitra discovered higher odds of obesity in the third tertile of PRO regarding Fat Mass and Obesity Associated Gene (FTO) and beta-2-adrenergic receptor (ADRB2) gene variants." (PMID 38397196, 2024). "The AT genotype represents an intermediate phenotype, illustrating the dose-dependent effect of the FTO gene’s allelic variations on obesity and related behaviors." (PMID 39203789, 2024). "A study on a homogeneous Polish population showed that the effect of SNPs in the first intron of the FTO gene on obesity is modulated by age and sex; this was particularly noticeable in men aged 45–50 years." (PMID 39458556, 2024). "Although multiple examples of GWAS functionalization attempts exist, one of the most noteworthy examples is at the FTO obesity locus." (PMID 39421299, 2024). "Given its pivotal role in obesity regulation, the identification of effective inhibitors targeting the FTO protein is imperative for developing therapeutic interventions." (PMID 39494311, 2024). "The long interspersed nuclear element 1 (LINE1) retrotransposon has been identified as a specific substrate for fat mass and obesity-related gene (FTO), which facilitates the removal of N6-methyladenosine modifications from its targeted RNAs." (PMID 39301283, 2024). "Association between SNPs in FTO and MC4R gene with obesity were widely replicated in different ethnic groups." (PMID 38279121, 2024). "This is the first study to suggest atropine’s potential role in targeting FTO for obesity treatment." (PMID 39494311, 2024). "The initial focus on the FTO gene was due to its link with obesity, and for an extended period, the impact of obesity on various diseases has been a prominent research topic." (PMID 39175477, 2024). "Overexpression of FTO increases fat accumulation and induces obesity in mice, whereas knockdown of FTO reduces fat mass and obesity." (PMID 38363215, 2024). "For example, entacapone has been reported as a potential FTO inhibitor for the clinical treatment of metabolic syndromes such as obesity and diabetes." (PMID 39295872, 2024). "Studies on the interaction between the FTO gene and environmental factors suggest that the impact of this genotype on obesity can be significantly influenced by lifestyle choices." (PMID 39858551, 2024). "Unfortunately, there are no studies aimed at studying the rs12149832 polymorphism of the FTO gene in CAN, but there is evidence that the AG genotype of rs12149832 predisposes to obesity." (PMID 38724937, 2024). "Epigallocatechin gallate, an extract from green tea, was discovered to target FTO and then inhibit adipogenesis, exhibiting an anti-obesity effect." (PMID 38560499, 2024). "The FTO gene, recently identified as playing a significant role in obesity, impacts energy metabolism by disrupting the balance between energy and adipose tissue regulation when its activity is altered." (PMID 39494311, 2024). "The most pronounced PheWAS signals for FTO resided within the metabolic domain and included body mass index (BMI), obesity status, waist-hip ratio, and various bioelectrical impedance measures." (PMID 39080362, 2024). "FTO is the first m6A demethylase and it exhibits a strong correlation with weight gain, obesity and other metabolic diseases in humans." (PMID 39054967, 2024). "Among the evaluated SNP of FTO gene in children and adolescents with obesity, only five SNPs (rs9939609, rs1421085, rs1861868, rs1477196 and rs17817449) were assessed in several studies." (PMID 38973101, 2024). "Another possible FTO role in obesity is the regulation of macronutrient intake due to the involvement of FTO expressed in the hypothalamus." (PMID 38892547, 2024). "The FTO gene has been considered as one of the most important genetic factors regulating the body weight and participate in the development of obesity." (PMID 39706986, 2024).